CD4 (CD4 molecule)
Diseases named in the same sentence as CD4 in open-access papers (continued):
Sharing a sentence is not in itself a finding about the gene and the disease.
tumor (continued). "While ATRA induced differentiation of MDSC into myeloid dendritic cells in vitro, administration in vivo increased MDSC differentiation and enhanced CD4+ and CD8+ T cell antigen specific immune responses, but did not decrease tumor burden." (PMID 23508517, 2013). "Our study further suggested that the re-activation step also triggers CD4+ T to express and exocytose cytotoxic molecules for directly killing MHC-II-restricted tumor cells and MHC-II-non-restricted tumor cells in the close proximity." (PMID 23145026, 2012). "The distribution of naïve, CD45RA+, CD4+ and CD8+ cells was similar in the tumor and the surrounding mucosa (data not shown)." (PMID 22319577, 2012). "In the present study, we found that the percentages of CD3+ T lymphocytes and CD4+ T lymphocytes, as well as the CD4+/CD8+ ratio, of tumor-bearing rats was lower than that in the non-tumor-bearing group before operation." (PMID 23139816, 2012). "This abscopal effect was dependent of CD8+ lymphocytes, CD4+ lymphocytes, and NK1.1 cells, but independent of the tumor-type and genetic background." (PMID 22848871, 2012). "In the absence of CD8+ cytotoxic T cells CD4+ cells are critical, and sufficient for NKT cell-dependent rejection of experimental tumours." (PMID 22375962, 2012). "By depleting mice of either CD4+ or CD8+ T cells, indications were found that CD4+ T cells but not CD8+ T cells were critical in the production of antibodies to LTAg and in tumour immunity." (PMID 22489251, 2012). "Anti-tumour antibodies are increased in AIRE−/− mice, but they are not CD4 dependent (IgM) and are not protective." (PMID 22506061, 2012). "Ii silencing in certain tumor cells downmodulates CLIP, but not HLA-II expression levels and results in increased presentation of endogenous antigens and tumor-specific CD4+ T cell activation." (PMID 22563374, 2012). "CD8+ T cells primed in the absence of CD4+ T cell “help” yielded so-called “helpless” CD8+ T cells that exhibited diminished clonal expansion, cytokine production, and ability to lyse tumor cells." (PMID 24212804, 2011). "Unfortunately, the role of CD4 T cells and the precise mechanisms by which CD8 T cells promote tumor dormancy were not reported." (PMID 24212638, 2011). "Direct tumor recognition in all cases was antigen-specific and HLA-DR-restricted since tumor cell lines not expressing the appropriate antigen (STEAP, EZH2), and the corresponding HLA-DR molecule failed to stimulate the CD4 T-cell responses." (PMID 22053850, 2011). "These standardized methods were previously shown to detect NY-ESO-1-specific circulating CD4+ and CD8+ T cell responses only in NY-ESO-1-seropositive patients with NY-ESO-1-expressing tumor, but not in healthy donors with low frequency of precursors." (PMID 21858191, 2011). "The role of CD4+ T and B lymphocytes is controversial in many cancers including STS; CD4+ cells in the absence of the CD8+ cytotoxic T cells are critical and sufficient for NKT cell-dependent rejection of experimental tumours." (PMID 21298041, 2011). "Not surprisingly, both CD4+ and CD8+ T cells were observed around the tumour tissues, while recruitment of the same subtype of T cells was almost non-existent in the PBS control group." (PMID 21176167, 2010). "During the effector phase in BALB/c mice, only depletion of CD4+ and CD8+ in combination, with or without NK cells, completely abrogated tumour protection." (PMID 20657846, 2010). "When tumour rejection was studied in knock-out mice with a C57Bl/6 background, protection was lost in CD4−/−CD8−/− and CD4−/−, but not in CD8−/− mice." (PMID 20657846, 2010). "Subsequent cell depletion experiments in immune competent mice revealed that CD8+, but not CD4+ cells were required for the anti-tumor effect, suggesting that cytotoxic T cells play an important role in CXCL12-mediated tumor inhibition." (PMID 20849618, 2010).
tumor (continued). "Depletion of CD4+ and CD8+ cells in combination, with or without depletion of NK cells, almost completely abolished the anti-tumour effect." (PMID 20657846, 2010). "Similar to BALB/c mice, protection against tumour outgrowth was obtained in both normal and CD8−/− mice, but not in CD4−/−CD8−/− mice." (PMID 20657846, 2010). "The T CD4+ lymphocyte count was not statistically different between patients without CIN and patients with low or high-grade neoplasia." (PMID 21120429, 2010). "Using immunohistochemical staining of tumors (not shown), both CD4+ and CD8+ cells were observed to infiltrate into tumors, although CD4+ cells do not appear to be required for tumor regression." (PMID 21050466, 2010). "Adoptive transfer of B/I activated tumor draining lymphocytes induces regression of advanced 4T1 tumors, and depletion of CD8, but not CD4 T cells, abrogated tumor regression in mice." (PMID 21050466, 2010). "Although the distributions of the CD4 and CD8 markers were rather stochastic in the tumor cells analyzed, we did find that single positive T–cells were usually skewed towards the CD8+ rather than to the CD4+ lineage." (PMID 20011522, 2009). "Consequently, this should also give rise to a larger number of CD8+ but not CD4+ Treg clones that in turn should serve to dampen local immune responses, and thus may explain enhanced tumor growth in the fully chimeric skin or the chimeric organs of the partial chimeras." (PMID 19087311, 2008). "Despite the better prognosis in patients with DARPP-32-positive tumours, the expression of DARPP-32 in OSCC was not correlated with infiltration of CD4+ and/or CD8+ T cells (P=0.7409; χ2 test)." (PMID 15188007, 2004). "A small number of infiltrating cells including CD4+, CD8+ and NK cells were scattered near most tumour foci (data not shown)." (PMID 12177809, 2002). "While our multi-round tumor challenge assay did not reveal a clear enhancement of CAR-iCD8+ T cell function by CAR-iCD4+ T cells, the consistent dominance of iCD8+ T cells in the CD4/CD8 co-culture group suggests functional interplay between the two subsets." (PMID 41484912, 2026). "In addition, pretreatment with IPG1576 not only increased the number of CD4+ and cytotoxic CD8+ cells but also altered the distribution of T cells within the tumor, promoting greater infiltration into the tumor core rather than the periphery." (PMID 41545340, 2026). "However, no increase in tumor PD-L1 expression and T-cell infiltrates (CD8+, CD4+, and FOXP3+ cells) was observed in the on-study biopsy of patients derived from the CRC cohort." (PMID 40649207, 2025). "In contrast to our previous findings in STING wild‐type tumor models, P2 treatment did not significantly alter the frequency of intratumoral immune (CD45+) and total T (CD3+) cell infiltration, and CD4+ and CD8+ T cells in STING KO tumors." (PMID 40789065, 2025). "Similarly, tumor-infiltrating CD3+, CD8+, activated CD4+, and activated CD8+ T cells, but not CD4+ T cells, were upregulated by treatment with cilengitide, AR-A014418, or WP1066." (PMID 40131864, 2025). "Unlike general CD8+ or CD4+ T cells, PD-1 expression may reflect exhaustion or activation; PD-1 on TEM cells specifically marks a subset with enhanced functional potential for tumor eradication." (PMID 41451213, 2025). "This change in hypoxia detected by PAI was correlated with strong positive correlations with CD8+ and CD4+ FoxP3- effector T cell (Teff), and negative correlations with monocyte frequencies, indicating that ITPP promoted more immunogenic tumor microenvironments in both models." (PMID 40594309, 2025). "Notably, there is a significant decrease in CD4+, CD8+, and CD3+ T cells at both tumor sites and tumor/non-tumor interface zones." (PMID 40831928, 2025).
tumor (continued). "In contrast, the lack of an effect of CD4+ T cell depletion on B16F10-ULBP2 tumor growth suggests that additional mechanisms, potentially via direct interference with NKG2D on CD8+ T cells, contribute to the suppression of anti-tumor immunity in this context." (PMID 40243581, 2025). "Notably, neither CD4+ nor CD8+ T‐cells exhibited an increase, further supporting that the reduction in tumor burden was driven by the MDCa@RBC‐Alipo‐induced innate antitumor immunity." (PMID 40289661, 2025). "However, the development of human CD4+ and CD8+ T cells was impaired in the blood and spleen but not in the tumor of NSG-Quad mice." (PMID 40503011, 2025). "Moderate-dose exercise did not alter the effects of PTX on the proportion of CD4+ T lymphocytes, CD8+ T lymphocytes, myeloid-derived suppressor cells (MDSCs), CD11b+/F4/80+ macrophages among leukocytes within the tumor tissue." (PMID 40302791, 2025). "To assess how key effectors in the adaptive immune system contribute to the protective anti-tumor response triggered by OpdA, we used genetically modified animals lacking IFN-γ and performed in vivo depletion of CD4+ and CD8+ T lymphocytes using specific monoclonal antibodies." (PMID 41019059, 2025). "Similarly, in mice bearing CT26 tumors, independent depletion of NK cells, CD8 T cells or CD4 T cells did not completely abrogate anti-tumor efficacy (9% (P > 0.337), 11% (P = 0.303), 42% (P < 0.001) GRI vs. vehicle control in CD4 depleted mice)." (PMID 40315226, 2025). "The rejection of tumors upon secondary rechallenge was only CD4 + T cell-dependent and not CD8 + T cell dependent, as the cured hosts depleted of only CD8 + T cells were able to reject a secondary tumor rechallenge similar to the cured, T cell sufficient hosts." (PMID 40585246, 2025). "CD4‐ and CD8‐positive T lymphocytes infiltrated the tumor tissue at various levels, and specimens with negative or value 1 (weak) staining were classified as the low‐infiltration group, while those with value 2 (moderate) or 3 (strong) staining were classified as the high‐infiltration group." (PMID 41187938, 2025). "Furthermore, captopril modulates the immune response to tumors by increased infiltration of CD3+, attenuated tumor-infiltrating CD4+, and expression of checkpoint receptor PD-1 on the CD8+ cells and CD4 and CD8 double-negative T cells." (PMID 40806350, 2025). "In contrast, while Lac or PD-1 antibody treatment did not significantly alter infiltration of CD4+ and CD8+ T cells into tumors (Fig. EV5D,E), these treatments activated tumor-infiltrating T cells as revealed by enhanced expression of IFNγ and perforin (J and EV5F)." (PMID 39979425, 2025). "Within the tumor microenvironment (TME), 4-OI reduced the frequencies of CD8+ and IFNγ+ CD8+ T cells, but had no significant impact on CD4+, Foxp3+ CD4+ T cells, or myeloid-derived suppressor cells (MDSCs), including monocytic (M-MDSC) and granulocytic (M-MDSC) subsets." (PMID 40521193, 2025). "To evaluate for potential peripheral conversion of Tregs, in a separate experiment, we instead adoptively transferred CD4+Foxp3–GFP– non-Tregs into LLC-bearing B6CD4–/– recipients, which did not demonstrate any conversion to Tregs in the tumor microenvironment." (PMID 40553564, 2025). "Notably higher numbers of CD4+, CD8+ and Tregs have been detected in the peritumoral region, rather than the tumoral region itself (tumor stroma and tumor nests)." (PMID 41150099, 2025). "Whereas depletion of CD4+CD25+Foxp3+ Tregs inhibited tumor growth and enhanced infiltration and function of CD8+ T cells in vivo, Gal1 knockdown failed to further improve the anti‐tumor effect in Treg‐depleted mice." (PMID 39853961, 2025). "It was predicted that at steady-state trough, this would lead to 72% of patients with an RG6292 concentration above the Treg (%CD4) EC50 in the tumor (positive effect) and 40% of patients with an RG6292 concentration above the non-Treg (%CD4) EC50 in plasma (potentially negative effect)." (PMID 39983024, 2025).
tumor (continued). "This includes hypermethylation at CCL2, CD4, IFNG, and TNF, which may contribute to non-inflamed tumor microenvironment (TME) phenotypes and reduced efficacy of immune checkpoint inhibitors (ICIs)." (PMID 40332491, 2025). "There was a 13.8% increase in immunosuppressive FoxP3+ CD4+ T cells as a total percentage of T cells in KEAP1 KO versus WT tumors; however, we did not detect a difference in the activation state of anti-tumor CD8+ T cells or NK cells." (PMID 41462606, 2025). "For example, CD4+ T cells, undefined CD45+, CD8+ T cells, and M0 macrophages CD68+ were much more abundant in the collagen-rich area of AGCT-1 in comparison with AGCT-2, whereas immune cell composition within the tumor area was not significantly different." (PMID 41042551, 2025). "In another series of experiments, we found that treatment with anti-CD25 mAb PC-61, which reduced the absolute number of intratumoral Tregs without concomitant activation of CD4+ Tconv, did not have any impact on CD45−CD31high tumor endothelial cells, MECA-79− TA-ECs, and MECA-79+ TA-HECs." (PMID 40460830, 2025). "In the TIME, a large number of inactivated CD4+ and CD8+ T cells and CTLs undergo apoptosis because of the absence of effective presentation of tumor-specific antigens and the influence of several cytokines with inhibitory effects; a process that was shown to be reversed by curcumin." (PMID 40940890, 2025). "Taken together, these results suggested that CBD-mediated tumor inhibition is mediated by both CD4+T and CD8+T cells, and that CBD can be growth stimulatory in vivo in the absence of CD4+T cells, suggesting a powerful influence of CD4+T cells in mediating CBD immune inhibition of tumor growth." (PMID 40475776, 2025). "The depletion of CD8+ T cells or simultaneous depletion of CD4+ T and CD8+ T cells resulted in exaggerated tumor growth in both combination therapy-treated and untreated mice, and combination therapy had no tumor suppression effect, demonstrating the importance of CD8+ T cells." (PMID 40897896, 2025). "It suggested that when M-TLSs abundance was comparable, the predominant cells mediating antitumor immunity in M-TLSs within the tumor region were proliferating CD20+ B cells, CD21+ cells, and CD4+ Th cells, rather than proliferating CD8+ cytotoxic T lymphocytes." (PMID 40918107, 2025). "Compared with combination therapy with alisertib and anti-IgG, combination therapy with alisertib and anti–B7-H3 mAbs significantly increased the abundance of total CD3+ T cells, tumor-infiltrating CD8+ T cells, perforin+ cells and granzyme B+ cells but not total CD4+ T cells." (PMID 39928563, 2025). "It is possible that the limited IL-2 production by intratumoral CD4+ T cells could be in part due to GSDMD inactivation, since a portion of CD4+ T cells did not display GSDMD activation in tumor sections." (PMID 40759573, 2025). "Additionally, 43% of CD8+ responses were detected in the tumor after infusion (CD8+: 13/30 tested, median 2; CD4+: not tested in tumor after infusion)." (PMID 39753970, 2025). "For example, if the expression of the HLA-I/HLA-II molecules is suppressed or impaired, epitopes of the peptides/HLA-II molecules introduced to the tumor may not be adequately presented to CD8+ and CD4+ T cells, the function of which might be impaired as well." (PMID 41002395, 2025). "Notably, only M002-treated CD4+ T cells and cluster 2 cells, but not saline-treated counterparts, interacted with tumor cells via MHCII pathways, specifically H2Ab1-Cd4 interactions." (PMID 39885128, 2025). "Thus, lack of proper tumor immunity is not due to the absence of immunogenicity but due to the increased infiltration and conversion of CD4+ CD25- T cells to CD4+ CD25+ T cells in HCC." (PMID 38571964, 2024). "Furthermore, CD4 + T cells, but not CD8 + T cells, were significantly increased inside the MASH-HCC tumor." (PMID 39402682, 2024).
tumor (continued). "Non-regulatory CD25+ CD45RA+ CD4+ T cells and CCR2 on granulocytes may boost the immunosuppressive characteristics of the tumor environment, thereby promoting LUAD progression." (PMID 39668823, 2024). "Compared with the model group, the combined treatment of DSF/Cu and DTX increased CD3+ T cells in the spleen of tumor-bearing mice (p < 0.05), among which the proportion of CD8+ T cells was significantly increased (p < 0.001), and the number of CD4+ T cells increased with no statistical difference." (PMID 38370371, 2024). "Interestingly, despite no MAGE 3-specific CD4+ and CD8+ T cell responses detected in peripheral blood, there was an increase in NK cells at tumor-infiltrated sites in 8 patients." (PMID 39174509, 2024). "At the same time, loss of NF1, TSC1, or TβRII promoted the production of soluble inflammatory mediators such as IL6 and IDO1, which resulted in a non-cell-autonomous immune-suppressive tumor microenvironment that is characterized by increased LAG3+ CD8 and CD4 T cells." (PMID 38997291, 2024). "Also, when patients did not experience anti-tumor benefits from therapy, the HIV parameters (e.g., viral titer, CD4 + T cell counts) were unchanged or improved during treatment." (PMID 39609320, 2024). "Tumor cells express CD3, CD4, and CD30; cytotoxic molecules and EBER are negative." (PMID 38611591, 2024). "Collectively, our findings suggest that HPV+ tumor cells could interact with CD4+T cells, likely through MHC-II recognition independent of traditional APCs, facilitating anti-tumor immunity." (PMID 39105803, 2024). "We appreciate that the use of high affinity transgenic CD4 T cell and B cells in combination with lymphopenic RAG-/- mice and a transplantable tumour line is an artificial system and does not recapitulate the complexities of the adaptive immune systems interaction with cancer." (PMID 38125720, 2024). "Decreased IFN-γ expression was observed in tumor-infiltrating CD8+ T cells from the Id2fl/flCd4-Cre+ mice in comparison with their Id2fl/flCd4-Cre− littermates, while no such difference was observed in CD4+ T cells." (PMID 38287103, 2024). "It showed non-MDSC tumor-resident myeloid populations produced CCL5 in response to CD40 activation, but not in response to immune checkpoint blockade, and CCL5-recruitment of CD4+ T cells mediated treatment efficacy." (PMID 38786066, 2024). "While targeting CD4+ cells had little effect, absence of CD8+ cells led to tumor regrowth." (PMID 38267628, 2024). "Pathological analysis indicated that all cases harbored immunoblastic/anaplastic or large tumor cells that expressed CD3 and CD30 by immunohistochemical analysis; however, expression levels of the T-cell subset markers CD4 and CD8 were inconsistent, and some cases did not express either." (PMID 38780761, 2024). "When examining the tumor, there was a significantly higher number and frequency of IFN-γ–positive CD8+ and CD4+ T cells alongside a significantly higher number, but not frequency of CD8+ and CD4+ T cells expressing Ki-67." (PMID 37917174, 2024). "The density of Tregs in the tumor remained unaffected by either the therapy or macrophage depletion, leading to a halving of the CD8 T cell to Treg ratio, with a lesser non-significant reduction in the CD4 Teff to Treg ratio." (PMID 38517331, 2024). "In addition, unlike CD4 and CD8 cells, which are infiltrating tumor cells, IL2Ra-positive cells are mainly located within and around areas of necrosis, which is expected of regulatory cells." (PMID 39769460, 2024). "Unlike tumor eliminating CD8+ T cells, the clinical significance of CD4+ T cells is controversial." (PMID 39264227, 2024). "Notably, based on the increase in tumor volume over four weeks, depletion of CD8+ T cells significantly abrogated the therapeutic effect of A2-APM (P = 0.042), whereas depletion of CD4+ T cells did not (P = 0.140)." (PMID 38320994, 2024).